SLC13A5 (solute carrier family 13 member 5)
Description:
High-affinity sodium/citrate cotransporter that mediates the entry of citrate into cells, which is a critical participant of biochemical pathways. May function in various metabolic processes in which citrate has a critical role such as energy production (Krebs cycle), fatty acid synthesis, cholesterol synthesis, glycolysis, and gluconeogenesis. Transports citrate into the cell in a Na(+)-dependent manner, recognizing the trivalent form of citrate (physiological pH) rather than the divalent form. Can recognize succinate as a substrate, but its affinity for succinate is several fold lower than for citrate. The stoichiometry is probably 4 Na(+) for each carboxylate, irrespective of whether the translocated substrate is divalent or trivalent, rendering the process electrogenic. Involved in the regulation of citrate levels in the brain (By similarity).
Synonyms: NaCT; INDY; mINDY; DEE25; EIEE25
Tractability: Small molecule: a structure with a bound ligand is known; a high-quality ligand is known. Antibody: UniProt places it where antibodies can reach, with high confidence; its Gene Ontology location is reachable by antibodies, with high confidence; UniProt predicts a signal peptide or a membrane-spanning region. PROTAC: its protein half-life has been measured; a small molecule that binds it is known.
Target class: SLC13 family of sodium-dependent sulphate/carboxylate transporters; Electrochemical transporter; SLC superfamily of solute carriers; Transporter
Chemical probes: BI01383298 (high quality)
Gene: Protein-coding gene on chromosome 17 (6,684,715 to 6,713,377, reverse strand). Ensembl gene ENSG00000141485.
Subcellular location: Cell membrane
Subcellular location (Human Protein Atlas): Nucleoplasm; Plasma membrane
Pathways (Reactome):
Transport of small molecules: SLC-mediated transport of organic anions
Gene Ontology:
Molecular function: citrate transmembrane transporter activity; organic acid:sodium symporter activity; protein binding; sodium:dicarboxylate symporter activity; succinate transmembrane transporter activity; solute:sodium symporter activity; transmembrane transporter activity; tricarboxylic acid transmembrane transporter activity
Biological process: alpha-ketoglutarate transport; cellular response to lithium ion; citrate transport; fumarate transport; oxaloacetate transport; succinate transport; transmembrane transport; sodium ion transmembrane transport; succinate transmembrane transport; tricarboxylic acid transmembrane transport
Cellular component: plasma membrane; membrane
Genetic constraint (gnomAD): Loss-of-function variants: 22 observed, 57.17 expected, observed/expected ratio (o/e) 0.38, 90% interval 0.27 to 0.55. The upper end of that interval is the gene's LOEUF score, 0.55, which puts it in group 2 of 6, group 1 being the genes least tolerant of losing a copy. Missense variants: 636 observed, 751.76 expected, observed/expected ratio (o/e) 0.85, 90% interval 0.79 to 0.9. Synonymous variants: 299 observed, 309.11 expected, observed/expected ratio (o/e) 0.97, 90% interval 0.88 to 1.06.
Homologues: Orthologues: chimpanzee SLC13A5 (99% identical), macaque SLC13A5 (93% identical), rabbit SLC13A5 (88% identical), pig SLC13A5 (85% identical), dog SLC13A5 (85% identical), guinea pig SLC13A5 (78% identical), rat Slc13a5 (78% identical), mouse Slc13a5 (75% identical), zebrafish slc13a5b (61% identical), zebrafish slc13a5a (58% identical), Caenorhabditis elegans nac-1 (39% identical), Caenorhabditis elegans nac-3 (37% identical), and 6 more. Paralogues in human: SLC13A2 (54% identical), SLC13A3 (48% identical), SLC13A1 (43% identical), SLC13A4 (43% identical), OCA2 (19% identical).
Diseases named in the same sentence as SLC13A5 in open-access papers:
SLC13A5 is named in the same sentence as 86 diseases in open-access papers, as found by Europe PMC text mining. Sharing a sentence is not in itself a finding about the gene and the disease. The quoted sentences say what the papers report.
epilepsy (22 papers, 2015 to 2025). A brain disorder characterized by episodes of abnormally increased neuronal discharge resulting in transient episodes of sensory or motor neurological dysfunction, or psychic dysfunction. "To explore epilepsy-related phenotypes due to the loss of SLC13A5 and study the molecular mechanisms behind this disorder, we generated the genetic mutants of both zebrafish SLC13A5 paralogs, slc13a5a (referred to as 5a) and slc13a5b (referred to as 5b)." (PMID 40208862, 2025). "Individuals suffering from SLC13A5 epilepsy harbor either homozygous or compound heterozygous SLC13A5 pathogenic variants." (PMID 40208862, 2025). "Functional research, such as citrate uptake assays, is needed to elucidate the underlying mechanisms of the mutation’s defects in SLC13A5-related epilepsy." (PMID 40313595, 2025). "These iPSC-based models promise to clarify how neurons with SLC13A5 variants respond to changes in citrate levels while elucidating the molecular and cellular mechanisms underpinning epilepsy and drug resistance in individual patients." (PMID 38392976, 2024). "The precise pathophysiology underlying how SLC13A5 loss-of-function results in epilepsy refractory to treatment is a subject of open and ongoing research." (PMID 38392976, 2024). "This is perhaps among the first few case reports of early neonatal epilepsy due to SLC13A5 mutation from India." (PMID 39723324, 2024). "The combination of iPSCs derived from patients harboring SLC13A5 variants and CRISPR-Cas9 technologies can help define the causative role of specific mutations and support the identification of biomarkers associated with SLC13A5 epilepsy." (PMID 38392976, 2024). "SLC13A5 iPSC-derived cellular models can be utilized to study epilepsy caused by metabolic disturbances." (PMID 38392976, 2024). "SLC13A5 (Solute carrier family 13 member 5) deficiency causes neonatal epilepsy that is refractory to treatment." (PMID 38392976, 2024). "The cardinal feature of SLC13A5 mutation is epilepsy with onset in the first week of life and impaired development of neurocognition later on." (PMID 39723324, 2024). "Mutations in the SLC13A5 gene are implicated in epilepsy and are associated with SLC13A5 citrate transporter disorder." (PMID 36984771, 2023). "As such, our results should motivate further investigation into the impact of SLC13A5 mutations on homeostasis of potentially toxic metal cations such as Zn2+ and its relation to epilepsy." (PMID 34525352, 2021). "Accumulating evidence reveals that several non-synonymous mutations of the SLC13A5 gene are phenotypically linked to neonatal epilepsy, developmental delay, and tooth hypoplasia." (PMID 34677420, 2021). "Loss-of-function mutations in SLC13A5 have been associated with early-onset epilepsy, but the role of citrate metabolism in the pathophysiology of these patients is not well understood." (PMID 34525352, 2021). "If SLC13A5-associated epilepsy arises solely due to insufficient amount of energy in neurons, why doesn’t it respond to the administration of alternative energy substrates?" (PMID 28264506, 2017). "Loss-of-function mutations in SLC13A5 are associated with early onset epilepsy in children; epileptic symptoms appear within the first few weeks after birth and seizures persist even as the affected children grow." (PMID 28264506, 2017). "Recently however, loss-of-function mutations in human SLC13A5 have been found to cause severe epilepsy and encephalopathy early in life." (PMID 28264506, 2017). "Only then would we be able to come up with appropriate therapeutic strategies to treat epilepsy in children affected with the loss-of-function mutations in SLC13A5." (PMID 28264506, 2017). "Loss of function of either SLC13A5 or SLC25A1 causes epilepsy even though the consequences of their loss of function on mitochondrial citrate levels are opposite." (PMID 28264506, 2017). "Plausible synaptic mechanisms linking loss-of-function mutations in SLC13A5 to epilepsy are discussed." (PMID 28264506, 2017).
epilepsy (continued). "In this context, it is important to note that mutations in the human SLC13A5 gene have been reported in neonatal childhood epilepsy with teeth hypoplasia or hypodontia in a recent study, a feature not observed in the whole body Slc13a5 knockout mice so far." (PMID 26647160, 2015). "Mutations in the SLC13A5 citrate transporter have been linked to epilepsy in humans." (PMID 40208862, 2025). "It remains unclear why children with mutations in SLC13A5 develop severe epilepsy and associated comorbidities." (PMID 40208862, 2025). "Similarly, dysregulation of citric acid cycle intermediates was found to alter TCA cycle metabolism in the SLC13A5 deficient patients with epilepsy." (PMID 41019533, 2025). "Horizontal genetic studies have found that SLC13A5 epilepsy is caused by newborn SLC13A5 mutations." (PMID 39121110, 2024). "Finally, citrate import is particularly important in human and mouse new-borns; mutations in Slc13a5 causing SLC13A5-epilepsy, a type of early-onset epileptic encephalopathy." (PMID 37872135, 2023). "To date, more than 40 known SLC13A5 variants that lead to epilepsy (including nonsense and missense variants, frame shift variants from single nucleotide polymorphisms, exon deletions, and whole gene deletions) are bi-allelic, with c.655G>A (p.G219R) and c.680C>T (p.T227M) being the most common." (PMID 36140822, 2022). "Virtually nothing is known on the molecular basis for the development of epilepsy in children with loss-of-function mutations in SLC13A5 except that the association between SLC13A5 mutations and epilepsy certainly indicates an obligatory function for the transporter in the brain." (PMID 28264506, 2017). "Any or all of these mechanisms might potentially underlie the pathogenesis of epilepsy in patients with SLC13A5 deficiency." (PMID 28264506, 2017). "Biallelic loss-of-function mutations in the SLC13A5 gene typically lead to DEE25, characterized by neurological manifestations such as epilepsy and psychomotor developmental delay." (PMID 40313595, 2025). "Individuals suffering from SLC13A5 epilepsy exhibit comorbidities, including cognitive impairments and sleep challenges." (PMID 40208862, 2025). "Brain MRI and EEG recordings from SLC13A5 epilepsy patients show punctate white matter lesions and abnormal brain activity, respectively." (PMID 40208862, 2025). "SLC13A5 deficiency diagnosis is performed by whole exome sequencing (WES) or by a targeted sequencing panel (SLC13A5 is included in multiple epilepsy panels) on affected patients." (PMID 38392976, 2024). "A challenge in studying SLC13A5 disease, especially epilepsy, is the limitation of available experimental models that accurately capture the complexity of the human brain." (PMID 38392976, 2024). "Epilepsy is the most common presentation of SLC13A5 citrate transporter disorder due to its neonatal onset." (PMID 37025451, 2023). "Discussion: These results show that in addition to the epilepsy phenotype, SLC13A5 citrate transporter disorder impacts global development, with marked abnormalities in motor abilities, tone, coordination, and communication skills." (PMID 37025451, 2023). "Notably, there is a lack of published reports on the NaCT protein expression in human neurons or brain tissue, despite the importance of SLC13A5 in epilepsy." (PMID 38392976, 2024). "This approach could further our understanding of the presence and nature of epileptic foci in SLC13A5 epilepsy." (PMID 38392976, 2024). "A key question in SLC13A5 epilepsy is whether patients have an epileptic focus, the specific site where seizures originate, characterized by abnormal electrical activity." (PMID 38392976, 2024). "We confirm that epilepsy is a pervasive symptom in SLC13A5 citrate transporter disorder." (PMID 37025451, 2023). "Given the citrate transporter activity of SLC13A5/INDY, it has been suggested that neuronal energy failure may cause SLC13A5-associated epilepsy." (PMID 34714823, 2021).
epilepsy (continued). "First, in many cases, the SLC13A5-associated epilepsy does not respond to ketogenic diets that provide alternative energy sources to the brain." (PMID 28264506, 2017). "This is a single-gene disease with epilepsy resulting solely from the inactivity of SLC13A5." (PMID 28264506, 2017). "Mechanistically, we show that 1) pharmacological inhibition or genetic knockdown of NMDA receptor signaling, and 2) treatment with zinc rescues the epileptic phenotypes, serving as the first empirical evidence for the ‘chelation hypothesis’ of SLC13A5 epilepsy." (PMID 40208862, 2025). "Interestingly, low glutamate levels in the cerebrospinal fluid (CSF) of SLC13A5 patients might impact the balance between excitatory and inhibitory neurotransmission, leading to epilepsy." (PMID 38392976, 2024). "Additionally, SLC13A5 is included in some commercially available epilepsy panels." (PMID 35847198, 2022). "Of even more concern is that loss-of-function mutations in human SLC13A5/INDY/Mindy do not lead to resistance to type 2 diabetes and instead cause neonatal epilepsy and several other developmental defects." (PMID 40535023, 2025). "A significant challenge in SLC13A5 epilepsy research is the absence of experimental models capable of faithfully replicating the complexity of human physiology, especially the complexities of neuronal circuits, while remaining accessible and easily manipulatable." (PMID 38392976, 2024).
Epileptic encephalopathy (19 papers, 2015 to 2026). A condition in which epileptiform abnormalities are believed to contribute to the progressive disturbance in cerebral function. "Background/Objectives:SLC13A5 encodes a sodium-citrate cotransporter implicated in early-onset epileptic encephalopathy and metabolic brain dysfunction, yet its developmental regulation and molecular context in the human brain remain incompletely defined." (PMID 41750164, 2026). "SLC13A5 citrate transporter disorder is a rare epileptic encephalopathy caused by loss-of-function pathogenic variants in the SLC13A5 gene." (PMID 41712282, 2026). "Autosomal recessive variants of the SLC13A5 gene (MIM*608305) have been reported to cause developmental and epileptic encephalopathy 25 with amelogenesis imperfecta (DEE25, MIM #615905) in early infancy." (PMID 40313595, 2025). "Biallelic (recessive) mutations in the human SLC13A5 gene cause developmental and epileptic encephalopathy 25 with amelogenesis imperfecta (DEE25, MIM #615905)." (PMID 40724960, 2025). "Among these, Slc13a5, mediating the cellular uptake of citrate is of special interest, as loss-of-function mutations are linked to seizures and epileptic encephalopathy." (PMID 36747230, 2023). "Developmental and epileptic encephalopathy 25 with amelogenesis imperfecta is a rare disease caused by variants in SLC13A5 genes." (PMID 37228816, 2023). "One such example is the epileptic encephalopathy SLC13A5 deficiency disorder, which is caused by loss of function pathogenic variants to the gene SLC13A5 that results in deficiency of the sodium/citrate cotransporter." (PMID 36140822, 2022). "Both variants in ROGDI and SLC13A5 cause epileptic encephalopathy and AI." (PMID 37228816, 2023). "Besides its important role for energy homoeostasis, NaCT also seems to be important for brain function and development because several mutations in the SLC13A5 gene encoding NaCT are associated with epileptic encephalopathies." (PMID 35448460, 2022). "Mutations in the SLC13A5 gene are associated with epileptic encephalopathy and developmental delay." (PMID 30054523, 2018). "Homozygous full‐length gene deletions mediated by Alu–Alu recombination are rare but have also been described, as with SLC13A5 in a family with epileptic encephalopathy." (PMID 41438488, 2025). "One of the proposed mechanisms that can help to control seizures in SLC13A5-epileptic encephalopathy is using medications that can increase the cytoplasmic level of citrate." (PMID 36923948, 2022). "This suggests smaller reductions in SLC13A5 activity are unlikely to recapitulate the autosomal-recessive epileptic encephalopathy phenotype observed with rare mutations affecting critical regions of the SLC13A5 gene." (PMID 38110950, 2023). "The EEG findings for SLC13A5 are not those of a severe epileptic encephalopathy, in which frequent or abundant interictal spikes are a dominant feature of the EEG and suspected as primary drivers of developmental, cognitive, and behavioral pathology." (PMID 37025451, 2023). "Until now, there is no specific treatment for SLC13A5-epileptic encephalopathy." (PMID 36923948, 2022).